IL2 (interleukin 2)
Diseases named in the same sentence as IL2 in open-access papers (continued):
Sharing a sentence is not in itself a finding about the gene and the disease.
tumor (continued). "Since reduced CD4 + T cell counts are associated with decreased levels of pro-inflammatory cytokines such as IL-2 in the circulation, we assume that despite an increase in some NK cell subsets, these effector cells are unable to mediate protective anti-tumor immunity in advanced tumors." (PMID 40783506, 2025). "In addition, the expression of CD107a and IFN-γ was markedly higher in tumor spheroid-activated T cells than in the IL-2-activated T cell group." (PMID 40123996, 2025). "Enrichment analysis revealed that low-scoring patients exhibit an activated tumor immune microenvironment, with upregulated pathways in interferon-γ and IL-2/STAT5, which can activate immune cells such as CD8 + T cells and natural killer cells, suggesting mechanistic links to ICI sensitivity." (PMID 41312055, 2025). "IL-15 appears less harmful to the TME than IL-2, as it fails to activate Tregs in a similar manner to IL-2, and occasionally inhibits Tregs.IL-15 may be more efficient than IL-2 in tumor suppression." (PMID 40469178, 2025). "Also, the overexpression of FDX1 in ccRCC cell lines suppressed tumor growth and strengthened the immune response against the tumor by enhancing the secretion of the TNFγ and IL-2." (PMID 41198664, 2025). "Our results demonstrated that US could spatiotemporally trigger production and secretion of IL-2 or sPD-1 in different syngeneic tumor mouse models, achieving robust therapeutic efficacy and minimizing toxic effects." (PMID 41041051, 2025). "Vascular normalization afforded through GPR4 inhibition may normalize tumor extracellular pH and stabilize IL2 protein." (PMID 40397803, 2025). "In preclinical studies using both anti-PD-1-sensitive and -resistant mouse tumor models, the mouse surrogate of AWT020 (mAWT020) demonstrated markedly enhanced anti-tumor efficacy compared to an anti-PD-1 antibody, IL-2, or the combination of an anti-PD-1 antibody and IL-2." (PMID 40046051, 2025). "Background/Objectives: Radiolabeled interleukin-2 (IL2) could allow for imaging activated T-lymphocytes in the tumor microenvironment (TME)." (PMID 40869484, 2025). "In the tumor immune microenvironment, CD4+ T cells can stimulate and maintain the differentiation of macrophages, CD8+ T cells and NK cells by secreting cytokines such as IFN-γ, TNF and IL-2, and inhibit angiogenesis of tumor, thus playing an anti-tumor effect." (PMID 40176817, 2025). "Moreover, PTX has been shown to inhibit IL-2 toxicity, preserve anti-tumor efficacy in patients with metastatic RCC." (PMID 41142779, 2025). "Similarly, in the E0771 tumor-bearing mouse model, the application of IL-2 neutralizing antibodies reduced the increase in Tregs induced by BTG2 knockout and mitigated the CTL functional inhibition caused by BTG2 deficiency." (PMID 40313959, 2025). "Indeed, ICI treatment followed by IL-2/JES6 administration potently inhibited tumor growth and completely cured 15 out of 16 experimental mice." (PMID 40789741, 2025). "Moreover, AHR-high expression was associated with inflammatory response, IL-2 and IL-6 signalling, and tumour necrosis factor alpha (TNF-α) signalling via NF-κB in both ER+ and ER- tumours." (PMID 40646277, 2025). "Similarly, we detect increased IFN-γ, TNF-α, and IL-2 expression in CD4+ T cells after coculture with RCOR2-KO tumor cells." (PMID 40608411, 2025). "Sun and other scientists have designed a recombinant IL-2 immune cytokine combining tumor-localizing antibodies and super mutant IL-2 (sumIL-2), which specifically binds to tumor cells and cytotoxic T cells (CTLs), thus effectively enhancing the anti-cancer effect." (PMID 39958351, 2025). "Furthermore, PTX has been demonstrated to inhibit IL-2 toxicity while preserving anti-tumor efficacy in patients with metastatic renal cell carcinoma." (PMID 41142779, 2025).
tumor (continued). "Similar context-dependent behavior of CD25-biased IL-2 agonists was described in a recent study, which reported that Tregs within the tumor microenvironment are present at high baseline frequencies, and many exist in an activated, proliferative state due to local IL-2 and other biochemical cues." (PMID 40789741, 2025). "Additionally, Ccn1‐KO tumors demonstrated significantly higher protein levels of TNFα, IL2, and IFNγ in tumor and serum." (PMID 40287974, 2025). "However, excess IL-2 also promotes the expansion of regulatory T cells, which interfere with the resolution of inflammation and contribute to a pro-tumor environment, highlighting the dual role of IL-2 in immunomodulation." (PMID 41376630, 2025). "Tumor-derived active TGF-β greatly diminishes the anticancer effects mediated by IL-2." (PMID 40636453, 2025). "In contrast, Y45 or IL‐2 treatment left ≈10% and 35% Tcm cells in the tumor, respectively." (PMID 40108893, 2025). "Notably, the response of non‐tumor tissue was significantly stronger when comparing final concentrations of IFNγ and IL‐2 after treatment." (PMID 40952312, 2025). "Furthermore, in co-culture assays with CD8+ T lymphocytes, this inhibitor restored the production of proinflammatory cytokines such as IL-2 and enhanced the immune cells’ ability to eliminate tumor cells." (PMID 40574024, 2025). "The combination therapy of PD-L1 blockade and IDO inhibitor can improve anti-tumor effects by increasing the frequency of IL-2-producing and proliferating polyfunctional T cells within the tumor, and prolonging the duration and frequency of peripheral tumor-reactive lymphocytes at a later stage." (PMID 40861801, 2025). "Because of the heterogeneity among the different cell lines, a biopsy may be very helpful in assessing the effectiveness of IL-2 immunotherapy before its administration, as well as for the characterization of the tumor microenvironment." (PMID 41150778, 2025). "An oHSV expressing IL-2 (G47Δ-mIL2) enhances anti-tumor immune responses by releasing IL-2 locally." (PMID 40469178, 2025). "The use of antibody–cytokine fusion proteins, called immunocytokines, is especially attractive, as immunocytokines can deliver cytokines such as interleukin 2 (IL-2) to the tumor activating the patients’ own cytotoxic T cells while reducing Treg numbers within the tumor and adjacent lymph nodes." (PMID 40813233, 2025). "Compared to monotherapy, the IL-2 and sPD-1 combination significantly enhanced anti-tumor effects." (PMID 41041051, 2025). "Therefore, we isolated and cultured TIL from primary cutaneous SCC and HNSCC tumor samples and stimulated the IL-2 expanded TILs with PMA/ionomycin." (PMID 40114916, 2025). "However, the clinical utility of IL-2 as an anti-tumor therapeutic is limited by reports of severe toxicity and an opposing role of IL-2 in both effector and regulatory T-cell signaling." (PMID 39984775, 2025). "High-dose IL-2 therapies, such as Proleukin®, have demonstrated remarkable responses in highly selected patient subsets, but often lack efficacy in broader populations due to variability in tumor biology and immune landscapes." (PMID 39852848, 2025). "In particular, combining these approaches with syngeneic models could provide critical insights into the effects of P2X4R-targeting therapies on the tumour microenvironment and immune responses, such as IL-2 production." (PMID 40515881, 2025). "Recent progress in cell-based delivery systems, such as Treg cell-mediated transport of drug-loaded liposomes to tumor cells, provided an additional promising strategy to enhance cancer immunotherapy, especially through the delivery of IL-2 and immune checkpoint inhibitors." (PMID 40143046, 2025). "Rhizoma Drynariae can enhance tumor immune function by up-regulating IL-2 levels." (PMID 41011149, 2025).
tumor (continued). "Furthermore, the Lactobacillus casei BL23 strain has been reported to exert anti-tumor effects through the modulation of IL-2 signaling, which is known to promote proliferation of NK cells and enhance their cytotoxic activity against tumor cells." (PMID 41515150, 2025). "The binding of OX40L to OX40 on the surface of activated T cells significantly enhanced the proliferation and survival of CD4+ and CD8+ T cells and the secretion of IFN-γ and IL-2, while inhibiting the immunosuppressive activity of regulatory T cells, thereby amplifying the anti-tumor immunity." (PMID 41561762, 2025). "Antitumor effects have been demonstrated for fusion proteins composed of antibodies targeting different tumor-associated antigens (e.g., CEA, EDB, EDA, GD2, EGFR, FAP) and many cytokines of the common gamma chain receptor family (e.g., IL-2, IL-15, IL-15/IL15Rα, IL-21, IL-7)." (PMID 40370435, 2025). "IL-2 is pivotal for the proliferation, survival, and activation of NK cells, and it has been utilized in clinical settings to augment NK cell responses against tumor cells." (PMID 40255394, 2025). "In this context, it has been shown that Denileukin Difititox (DD), which is composed of IL-2 fused to the diphtheria toxin, can enhance anti-tumor immunity by interacting with the IL-2Rαβγ trimeric form selectively expressed on Treg cells, leading to their depletion." (PMID 39852848, 2025). "Of note, the epitope-directed approach to increase the concentration of IL-2 in the tumor as part of a fusion protein (L19-IL2), which was successfully combined with single high-dose RT, also resulted in intratumoral CD8+ T cell expansion with only minimal changes in secondary lymphoid organs." (PMID 40502703, 2025). "Notably, the TIM-3+ PD-1+ dual positive tumor-infiltrating T lymphocytes (TILs) are defined by their failure to proliferate with reduced expression of IL-2, TNF-α, and IFN-γ and these cells exhibit the most pronounced exhausted state." (PMID 40872312, 2025). "Especially the intra-tumor injection or inhalation of a human cytokine (IL-2, IL-12, IL-15) could be an attractive treatment option for certain canine cancers with minimal side effects and the possibility of inducing a vaccine-like effect." (PMID 40671820, 2025). "Further comparison of differential signaling flows between the two groups revealed a significant upregulation of signaling pathways associated with tumor metastasis, immune evasion, and inflammatory response, including TGFβ, EGF, and IL2, in the high mRNAsi group." (PMID 40963856, 2025). "Furthermore, GSEA analysis showed reductions in genes related to anti-tumor immune responses including the IL-2/STAT5, the interferon-gamma and the PI3K/AKT/mTOR signaling." (PMID 39885132, 2025). "Furthermore, in comparison to using the active form directly, the IL-2 prodrug elicited similar cytokine production within tumor sites while reducing peripheral inflammatory cytokine levels." (PMID 40557148, 2025). "Notably, the administration of IL-2 has been shown to exert strong anti-tumor effects and the ability to inhibit the progression of metastatic tumors in murine models." (PMID 40649958, 2025). "While we did observe increased frequencies of Granzyme B+ (GzmB+) T cells in the IL-2–expanded group compared with those expanded with IL-7, we also noted an increased baseline frequency of GzmB+ T cells in the unstimulated/IL-2–expanded and tumor-only control groups." (PMID 40244705, 2025). "This combination significantly increased CD4+ and CD8+ T cell infiltration within tumor tissue, markedly enhanced the cytotoxic activity of tumor-specific cytotoxic T lymphocytes (CTLs), and reversed both IL-2 depletion and elevated PD-L1 expression induced by sorafenib intervention." (PMID 40926993, 2025). "Preclinical studies have shown that this molecule effectively controls tumor growth without eliciting the systemic toxicities traditionally associated with high-dose IL-2 therapy." (PMID 40725830, 2025).
tumor (continued). "Moreover, the signaling of IL-2 through its receptor plays an important role in tumor immunity, promoting the activation, differentiation, and functional restoration of T cells, and providing potential strategies for tumor immunotherapy." (PMID 40496561, 2025). "The first involves the isolation of tumor-infiltrating lymphocytes (TILs) from immunologically active (“hot”) tumors, followed by their ex vivo proliferation using T-cell-stimulating cytokines such as interleukin-2 (IL-2)." (PMID 40649958, 2025). "Among these, IL-2 and TNF-α are especially relevant for T cell expansion and anti-tumor immunity, while IL-4 and IL-10, linked to Th2 responses, may play a lesser role in MM immune surveillance." (PMID 40948764, 2025). "CD4+ Tregs express high-affinity IL-2 receptors and expand in response to IL-2, which may limit the anti-tumor activity of activated CD8+ T cells." (PMID 38928238, 2024). "The inclusion of IL-2 in this treatment regimen is based on the reason of that an activated immune system can significantly augment the efficacy of direct cytotoxic effects on tumor cells, offering a dual approach to combating advanced NSCLC 23-24." (PMID 38434976, 2024). "Furthermore, GSEA analysis showed reductions in genes related to anti-tumor immune responses including the IL-2/STAT5 pathway, the interferon-gamma response and the PI3K/AKT/mTOR signaling." (PMID 38659818, 2024). "Notably, IL‐2‐Fc consistently caused the most significant decrease in tumor Tregs compared to ICK at this earlier time point, which translated into IL‐2‐Fc's significantly higher IFNγ+CD8+/Treg ratio in both models compared to controls and ICK." (PMID 38317590, 2024). "The chronopharmacology of interleukin-2 (IL-2) was shown in tumor-bearing rats, where constant rate infusions of IL-2 induced a 37.5% mortality rate and a 25% objective tumor response rate, whereas animals receiving a “day cycle” of IL-2 had no mortality and a 100% objective response rate." (PMID 38834742, 2024). "This phenomenon may also be exacerbated by limited IL-2 bioavailability in tumours, potentially due to PGE2-mediated induction of IL-2-scavenging regulatory T cells." (PMID 38658764, 2024). "Thus, even in a disadvantage environment such as low IL-2, loss of MCJ preserves the anti-tumor efficacy of CD8 CAR-T cells." (PMID 38789421, 2024). "Targeting cytokines such as IL-4, IL-17, IL-15, IL-2 and IL-6 could be an alternative way to create an inflamed tumor microenvironment." (PMID 38928238, 2024). "However, as activation of these genetically modified cells is dependent on exogenous IL-2, in vivo studies have shown reduced expansion, stability and anti-tumor activity of these CAR-T cells, as they lack interaction with co-stimulatory receptors." (PMID 39091493, 2024). "Earlier results have shown cytokines such as IL-2 could promote the regression of solid tumor models established in animals, providing novel insights for augmenting anti-tumor effects of immunocytes containing NK cell by cytokines." (PMID 38396050, 2024). "Consequently, the induction of IFN-γ, TNF-α, and IL-2 in tumor-infiltrating CD8+ T cells by LNP-pE285K-dIgA was inhibited upon Pigr knockdown." (PMID 38886748, 2024). "It is interesting to note here that IL-15 has similar functions to IL-2 in that it can stimulate the activation of T-cells, the generation of cytotoxic effector T-cells, and the activation of NK cells, all of which can reduce tumor growth." (PMID 39451257, 2024). "Interleukin-2 (IL-2) serves as a pivotal immunoregulatory molecule, eliciting a response from specific immune system components, including cytotoxic T lymphocytes and NKs, that are tasked with identifying and eliminating tumor cells within the body." (PMID 39267764, 2024).
tumor (continued). "Accumulating data also indicated that CD8+ T cells in tumor tissues are activated by antigenic stimulation, and IL-2 in the tumor microenvironment promotes their differentiation into cytotoxic T lymphocytes (CTLs) and infiltration into the tumor microenvironment." (PMID 38882349, 2024). "IL-2 is thought to drive anti-tumor immunity by enhancing the proliferation, survival, and effector function of lymphocytes that express the heterodimeric IL-2/IL-15 receptor (IL-2/15Rβ/common γ, CD122/CD132, Rβγ), such as NK cells, activated T cells, and resting memory CD8+ T cells." (PMID 38887559, 2024). "Further studies exploring types of radiation therapy, type of tumor, tumor location, as well as dosage and timing of IL‐2‐Fc will need to be explored, but our preliminary results show that this is a promising direction to take due to induction of immune memory." (PMID 38317590, 2024). "The chronic inflammatory response induced by tumour cells further enhances the infiltration of neutrophils, further promoting tumour progression through the secretion of interleukin-2 (IL-2), IL-6, IL-10, tumour necrosis factor-alpha (TNF-α), and vascular endothelial growth factor (VEGF)." (PMID 38496751, 2024). "Tumor growth curves for IL‐2‐Fc versus ICK therapy showed similar tumor growth inhibition." (PMID 38317590, 2024). "If this holds true, IL-2/IL-18-induced NK cells function as a bridge between innate immunity and adaptive immunity, challenging the conventional view of NK cells solely as innate immune effector cells that naturally eliminate tumor cells." (PMID 39195212, 2024). "This suggests that IL‐2‐Fc treatment causes a stronger initial antitumor immune response than ICK due to far better elimination of Tregs, but ICK appears to maintain this response better in the long term mainly by increased IFNγ+CD8+ T cell tumor infiltration." (PMID 38317590, 2024). "Besides, employing a non-IL-2 blocking anti-CD25 antibody, Tregs can be eliminated while retaining the responsiveness of effector T cells to IL-2 signaling, thus amplifying the proliferation and function of anti-tumor T cells." (PMID 38500876, 2024). "It remains to be seen whether such approaches will be able to overcome interpatient and intratumoral variability in protease expression and achieve sufficient discrimination between tumor and healthy tissue to widen IL2’s therapeutic index in patients." (PMID 38563906, 2024). "Consequently, IL-2 produced by infiltrating lymphocytes stimulates tumor STAT5A signaling, which, in turn, synergizes with TET2 to epigenetically elevate tumor cGAS expression, thereby establishing a positive feedback loop." (PMID 39107856, 2024). "In addition, IL-2 antagonizes TOX by driving STAT5 activity to exert anti-tumor immunity that reverses CD8+ Tex." (PMID 39372416, 2024). "CIK cells can kill tumor cells through multiple mechanisms, including the release of perforin and granzyme to directly lyse tumor cells, direct inhibition of tumor cells, or indirect regulation of immune function by secreting cytokines such as IL-2, IL-6, IFN-γ, and GM-CSF." (PMID 39221244, 2024). "In addition, NK cells also secrete IFN-γ, IL-2, and other multiple cytokines, which regulate and promote the activities of other immune cells, thereby improving immune response and inhibiting tumor development." (PMID 39450258, 2024). "The objective tumor responses were 44% (LAKs) and 40–60% (TILs) in conjunction with IL-2." (PMID 38668417, 2024). "In addition recent studies have highlighted the critical role of IL-2Rα in effective IL-2 induced anti-viral and anti-tumor responses and emphasize the pivotal importance of IL-2Rα binding in refining IL-2-based cancer immunotherapy." (PMID 39114660, 2024). "Tumour infiltrating lymphocytes (TILs) expanded by interleukin‐2 (IL‐2) plus anti‐PD‐1 could significantly infiltrate into the immune organoids and facilitate tumour‐killing effects." (PMID 39245957, 2024).